PARM1 (prostate androgen-regulated mucin-like protein 1)
Description:
May regulate TLP1 expression and telomerase activity, thus enabling certain prostatic cells to resist apoptosis.
Synonyms: PARM-1; DKFZP564O0823; Cipar1; WSC4
Tractability: Antibody: UniProt places it where antibodies can reach, with high confidence; its Gene Ontology location is reachable by antibodies, with high confidence; UniProt predicts a signal peptide or a membrane-spanning region.
Gene: Protein-coding gene on chromosome 4 (74,933,041 to 75,050,115, forward strand). Ensembl gene ENSG00000169116.
Subcellular location: Cell membrane; Golgi apparatus membrane; Endosome membrane
Subcellular location (Human Protein Atlas): Cytosol; Nucleoplasm; Vesicles
Gene Ontology:
Molecular function: protein binding
Cellular component: early endosome; Golgi apparatus; late endosome; plasma membrane; endosome membrane; Golgi membrane
Genetic constraint (gnomAD): Loss-of-function variants: 12 observed, 19.69 expected, observed/expected ratio (o/e) 0.61, 90% interval 0.39 to 0.99. The upper end of that interval is the gene's LOEUF score, 0.99, which puts it in group 4 of 6, group 1 being the genes least tolerant of losing a copy. Missense variants: 333 observed, 361.29 expected, observed/expected ratio (o/e) 0.92, 90% interval 0.84 to 1.01. Synonymous variants: 168 observed, 146.82 expected, observed/expected ratio (o/e) 1.14, 90% interval 1.01 to 1.3.
Homologues: Orthologues: chimpanzee PARM1 (98% identical), macaque PARM1 (94% identical), rabbit PARM1 (70% identical), pig PARM1 (68% identical), mouse Parm1 (62% identical), rat Parm1 (60% identical), tropical clawed frog parm1 (27% identical).
Diseases named in the same sentence as PARM1 in open-access papers:
PARM1 is named in the same sentence as 20 diseases in open-access papers, as found by Europe PMC text mining. Sharing a sentence is not in itself a finding about the gene and the disease. The quoted sentences say what the papers report.
prostate carcinoma (5 papers, 2010 to 2023). A carcinoma that arises from epithelial cells of the prostate gland. "Multiple works have proved that PARM1 is an important causal gene of prostate cancer." (PMID 25151146, 2014). "Elevated rat PARM1 expression was reported tocause enhanced telomerase function and the immortalization of prostate cancer cell lines,implying its role in the regulation of prostate cells’ survival." (PMID 33884106, 2021). "In the results, two of the four genes (TUBB6, PARM1) are supported by literature for their roles in prostate cancer; nonetheless, the other two (SLC25A22, MYEF2) are less known." (PMID 25151146, 2014). "In prostate cancer cells, PARM1 ectopic expression increased cell proliferation." (PMID 36950314, 2022). "PARM1 is part of the Golgi apparatus that is androgen-responsive, and researches demonstrate that the Golgi apparatus embody new mechanisms of the androgen receptor (AR)-mediated signaling and they are useful biomarkers for prostate cancer diagnosis/prognosis." (PMID 25151146, 2014). "Given this foreground, PARM1 may have the potential of a therapeutic target for prostate cancer." (PMID 25151146, 2014). "In contrast, in prostate cancer cell lines, and in human prostate cancer xenograft, CWR22, PARM-1 is constitutively expressed, and PARM-1 expression is positively regulated by androgen in CWR22 xenograft." (PMID 20305782, 2010). "Since they are co-interacting with PARM1 and MYEF2, ESR1 and NR3C2 may also participate in prostate cancer along with the existent/potential targets." (PMID 25151146, 2014).
colorectal cancer (4 papers, 2020 to 2023). A primary or metastatic malignant neoplasm that affects the colon or rectum. "In colorectal cancer, PARM1 may be its potential novel prognostic biomarker." (PMID 36950314, 2022). "PARM1 could suppress the proliferation of colorectal cancer cells." (PMID 32924329, 2020). "One, (PARM1) is a potential oncogene and prognostic biomarker for colorectal cancer with no known function in the brain." (PMID 34552157, 2021). "MeRIP-seq and RNA-sequencing revealed four genes, WD- repeat domain 72 (WDR72), spectrin beta, non-erythrocytic 2 (SPTBN2), microrchidia 2 (MORC2), and prostate androgen-regulated mucin-like protein 1 (PARM1), which could predict the prognosis of patients with colorectal cancers." (PMID 36835633, 2023).
leukemia (2 papers, 2013 to 2026). A malignant (clonal) hematologic disorder, involving hematopoietic stem cells and characterized by the presence of primitive or atypical myeloid or lymphoid cells in the bone marrow and the blood. "In the present study, probsets associated with T-CD8+ leukemias were analyzed and we validated the expression profile of the Parm-1 gene." (PMID 23902727, 2013). "We identified Parm-1 (prostate androgen-regulated mucin-like protein 1), a gene specifically up-regulated in T-CD8+ leukemias induced by Graffi virus." (PMID 23902727, 2013).
cardiac hypertrophy (1 paper, 2010). "While one of the early cardiac manifestations of this model is hypertension-induced cardiac hypertrophy, PARM-1 expression was unchanged 4 weeks after starting a high-salt diet, when a significant increase in LVW to BW ratio was already detected." (PMID 20305782, 2010). "In Dahl salt-sensitive rats, high-salt diet resulted in hypertension, cardiac hypertrophy and subsequent heart failure, and significantly stimulated PARM-1 expression in the hearts, with a concomitant increase in ER stress markers such as GRP78 and CHOP." (PMID 20305782, 2010).
cervical cancer (1 paper, 2021). A primary or metastatic malignant neoplasm involving the cervix. "The score for PAMR1 was significantly lower in cervical cancer tissues than in adjacent normal tissues, and the protein level of PARM1 was decreased in patients who had positive lymph node metastasis." (PMID 34671559, 2021).
epilepsy (1 paper, 2023). A brain disorder characterized by episodes of abnormally increased neuronal discharge resulting in transient episodes of sensory or motor neurological dysfunction, or psychic dysfunction. "There were 8 DEGs (Ldoc1, Nefh, Parm1, Ptpro, Pvalb, Spp1, Synpr, Vamp1) shared by the schizophrenia and epilepsy gene sets, suggesting a common molecular basis between the two disorders." (PMID 37545878, 2023).
heart failure (1 paper, 2010). Inability of the heart to pump blood at an adequate rate to meet tissue metabolic requirements. "In this model, PARM-1 was significantly upregulated 8 weeks after starting a high-salt diet, suggesting that PARM-1 was induced in the setting of heart failure." (PMID 20305782, 2010). "Further, ER stress inducers, thapsigargin and tunicamycin markedly upregulated PARM-1 expression, and ER stress markers such as GRP78 and CHOP were also upregulated in the hearts of hypertensive heart disease model at the heart failure phase." (PMID 20305782, 2010).
hypertensive heart disease (1 paper, 2010). Abnormal enlargement of the heart resulting from long-standing hypertension. "Our analysis on hypertensive heart disease model of Dahl salt-sensitive rats demonstrated that PARM-1 expression was significantly upregulated following a high-salt diet." (PMID 20305782, 2010). "In this study, we identified PARM-1 as an ER protein specifically expressed in cardiac myocytes, and found that PARM-1 expression was induced in hypertensive heart disease model, and by ER stress in cardiac myocytes." (PMID 20305782, 2010). "As PARM-1 expression was most significantly modulated in the hearts of hypertensive heart disease model of Dahl salt-sensitive rats, we focused PARM-1 in this study." (PMID 20305782, 2010).
Insulin resistance (1 paper, 2019). Increased resistance towards insulin, that is, diminished effectiveness of insulin in reducing blood glucose levels. "Prostate androgen-regulated mucin-like protein 1 (PARM1), ALDH4A1, VENTX, and KIAA0040 are novel biomarkers for the development of insulin resistance." (PMID 30678306, 2019).
mastitis (1 paper, 2023). Inflammation of breast tissue during lactation or postpartum due to an obstructed duct or infection. "Regarding the genes selected, the first latent variable of the expected model indicated that subjects with mastitis overexpressed the prostate androgen-regulated mucin-like protein 1 (PARM1) gene." (PMID 37403140, 2023).
osteosarcoma (1 paper, 2022). A usually aggressive malignant bone-forming mesenchymal neoplasm, predominantly affecting adolescents and young adults. "The data from this study suggest that PARM1 is closely associated with the prognosis of osteosarcoma patients, and PARM1 may serve as a novel potential prognostic target for osteosarcoma, providing a heartfelt direction for the prevention and treatment of osteosarcoma." (PMID 36950314, 2022). "Although we verified the heterogeneous expression of PARM1 in normal tissues and osteosarcoma cells in cellular experiments, to further explore the mechanism of action of PARM1 affecting the prognosis of osteosarcoma patients." (PMID 36950314, 2022). "PARM1 was lowly expressed in osteosarcoma tissues, and low expression of IFIT1 predicted a poor prognosis for patients." (PMID 36950314, 2022). "The results showed that the expression of IFIT1 was high and the expression of PARM1 was low in the osteosarcoma cell line saos-2." (PMID 36950314, 2022). "The results showed that overexpressing PARM1 in osteosarcoma cells significantly reduced the migration ability of cells (p<0.01)." (PMID 36950314, 2022). "In the previous data, we confirmed that low expression of PARM1 predicted poor prognosis in osteosarcoma patients." (PMID 36950314, 2022). "Then we detected the protein levels of IFIT1 and PARM1 in the osteoblast cell line hfob 1.19 and the osteosarcoma cell line saos-2 by WB." (PMID 36950314, 2022). "In conclusion, in our study, we identified PARM1 as a poor prognostic factor in osteosarcoma by bioinformatics based on the GEO database, and low expression of PARM1 predicted poor prognosis in osteosarcoma patients." (PMID 36950314, 2022). "Then the prognostic model was constructed by LASSO and Survival analysis identified PARM1 as a favorable factor for osteosarcoma patients." (PMID 36950314, 2022). "In addition, cellular experiments were performed to verify PARM1 was lowly expressed in the osteosarcoma cell line saos-2." (PMID 36950314, 2022). "In order to further verify the accuracy of our model construction, we built a prognostic risk model in the target database, and further tested that low expression of PARM1 indicates poor prognosis of osteosarcoma patients, which further verified the accuracy of our model." (PMID 36950314, 2022). "PARM1 was found to be a prognostic factor in osteosarcoma patients by LASSO regression analysis, followed by cellular assays to verify that PARM1 was lowly expressed in osteosarcoma cells and that overexpression of PARM1 in osteosarcoma cells inhibited cell migration." (PMID 36950314, 2022).
cancer (7 papers, 2013 to 2026). A tumor composed of atypical neoplastic, often pleomorphic cells that invade other tissues. "PARM-1 is a member of the mucin family known to be expressed at the surface of many epithelial cells to promote cell survival by protecting the cell surface and to be implicated in cancer development." (PMID 23902727, 2013). "Pan-cancer analysis showed that PARM1 was lowly expressed in most cancers and that low expression of PARM1 predicted poor prognosis for patients." (PMID 36950314, 2022). "PARM1 can enhance the survivability of cancer cells during the transportation and competing with the native cells in the invaded environment." (PMID 25151146, 2014). "We performed a pan-cancer expression and prognostic analysis of PARM1 and found that PARM1 showed a trend of low expression in most cancers, and low expression of PARM1 in COAD, KIRC, and LUAD predicted poor prognosis of patients, which also confirmed PARM1 as a poor prognostic factor." (PMID 36950314, 2022). "Our interest for this gene was drained by the fact that Parm-1 was poorly characterized and had never been clearly associated with cancer." (PMID 23902727, 2013). "Further studies are required to better understand PARM-1 functions and could provide new tools to develop new therapeutic approaches in the treatment of human cancer." (PMID 23902727, 2013). "It is known that mucins are implicated in cancer development but there were no convincing data yet on the role of Parm-1 in cellular transformation." (PMID 23902727, 2013). "Several other genes in our model have been independently verified as oncogenes (SPAG5, PARM1) or tumor suppressors (VEPH1, GLCE) in prostate or other cancers, showcasing the ability of our TET2-based model to capture these key changes." (PMID 33008340, 2020).
tumor (4 papers, 2020 to 2022). "Other genes identified included SPINK1, an inhibitor of apoptosis that has been associated with chemoresistance, and PARM1 which is an androgen-related gene that drives tumor proliferation." (PMID 35280731, 2022).
heart diseases (1 paper, 2010). "As elucidation of cardiac specific ER stress response could have therapeutic impacts on many heart diseases, identification of molecular mechanisms regulated by PARM-1 will be an important issue to understand cardiac specific ER stress responses." (PMID 20305782, 2010).
PARM1 also shares sentences with these, for which no sentence is quoted: bacterial infections (1 paper); cardiovascular diseases (1); Hypertension (1); mesothelioma (1); pulmonary arterial hypertension (1); schizophrenia (1).